FAM218A (family with sequence similarity 218 member A)
Synonyms: C4orf39; FLJ31659; TRIM61-AS1
Gene: Long non-coding RNA gene on chromosome 4 (164,956,946 to 164,959,122, forward strand). Ensembl gene ENSG00000250486.
Diseases named in the same sentence as FAM218A in open-access papers:
FAM218A is named in the same sentence as 1 disease in open-access papers, as found by Europe PMC text mining. Sharing a sentence is not in itself a finding about the gene and the disease.
FAM218A shares sentences with these, for which no sentence is quoted: ovarian tumors (1 paper).